CD34 (CD34 molecule)
Diseases named in the same sentence as CD34 in open-access papers (continued):
Sharing a sentence is not in itself a finding about the gene and the disease.
infection (continued). "The protein complex may cooperatively favor a latent state of infection since the replication advantage of UL133- and UL138-mutant viruses in CD34+ HPCs are not additive when combined." (PMID 32630219, 2020). "CD34+ cells were latently infected with wild-type Merlin virus, LUNASHORT virus, or a revertant virus and then assayed for DNA carriage between 3–10 days post-infection (dpi) in the absence of any cytokine stimulation." (PMID 30021158, 2018). "However, unlike in CD34+ cells, MCL-1 levels remain elevated in CD14+ monocytes until at least 48 h post infection (hpi), a long time after the initial binding events responsible for triggering its upregulation." (PMID 29547547, 2018). "However, apoptosis was also observed in some of the uninfected CD34+ HSCs population as the number of TUNEL+; apoptosis without infection was significantly higher than NP+TUNEL+; infected and apoptosis." (PMID 24339969, 2013). "Interestingly, after exposure to BECs, regardless of infection or TNF-α treatment, both CD16+ and CD16– monocytes lost their CD62L expression, possible due to binding with CD34, the endothelial cell ligand for CD62L, and subsequent cleaving and/or internalization." (PMID 33690725, 2021). "Regarding CXCR4 expression levels in different subsets, the frequencies of CD34+CD7+CXCR4+ cells in HIV+ samples (mean 2.08 ± 2.56%) were significantly reduced compared to those in HIV− samples (mean 2.49 ± 2.42%), regardless of the degree of infection (data not shown)." (PMID 30761146, 2019). "As a result, ex vivo expansion of CD34+ cells in StemCell media without EPO generates a culture with a predominant population of bipotent megakaryocyte-erythrocyte BFU-E progenitors, which in average only allows a very low B19V entry and basically no infection." (PMID 27690083, 2016).
hematological malignancies (66 papers, 2010 to 2026). "EMH is the generation of blood cells outside of the BM and is a hallmark of hematologic disorders, particularly MF, which among MPNs is characterised by the worst prognosis and by the mobilisation of CD34+ cells from the BM." (PMID 40690545, 2025). "For instance, a polymorphism of the CD44 gene is shown to impact CD34+ HSPCs cells mobilization from the BM niche into systemic circulation in hematological malignancies, with some alleles having poorer CD34+ cell mobilization than others." (PMID 34395425, 2021). "While our approach identified and partially characterized GSH candidates for gene therapy of blood disorders, the heterogeneity of primary CD34+ cell populations must be thoroughly considered." (PMID 41438051, 2025). "Taken together, these studies support anti-inflammatory, angiogenic and neuroprotective roles of expanded CD34+ cells, and emphasise the therapeutic potential of CD34 expansion for non-haematological diseases." (PMID 39075614, 2024). "We examined neonatal CD34+ cells, whose response to damage still needs to be extensively analyzed due to their clinical application in treatment of hematological malignancies." (PMID 37962865, 2024). "Regardless of the delivery approach, another crucial aspect of in vivo genome editing of blood disorders is how to make the human CD34+ HSPCs accessible for delivery." (PMID 36969373, 2023). "G-CSF-mobilized CD34+ progenitor cells are the most commonly used stem cell source for transplantation of adult patients with hematological malignancies." (PMID 37728691, 2023). "On the armamentarium to overcome these challenges, etoposide (topoisomerase II inhibitor) has been a widely used chemotherapeutic agent to facilitate the collection of CD34+ stem cells in patients with various hematologic diseases." (PMID 37835477, 2023). "CD34 expression of these stem cells has been exploited for therapeutic purposes in various hematological disorders." (PMID 37241170, 2023). "By means of FISH and molecular analysis on both sorted CD138 plasma cells and cryopreserved CD34 stem cells, a distinct clonal origin of the hematological malignancies was demonstrated in our case." (PMID 38024589, 2023). "Our data suggest that GRP78, CALR, PDIA3 and GPI released from irradiated MSC act as mediators of genetic instability in human CD34+ cells with potential implications for radiation-induced hematologic disorders." (PMID 35740549, 2022). "In the context of alloSCT for hematological malignancies, G-CSF mobilized CD34+ HPCs are the most commonly used source for transplantation." (PMID 33796917, 2021). "To this purpose, we selected a list of 13 lncRNAs deregulated in hematological malignancies both from literature and from preliminary gene-expression data in CD34+ cells." (PMID 34638230, 2021). "A breakthrough approach in hematologic diseases reported that using G-CSF to mobilize HSCs and hematopoietic stem cell progenitors (CD34+) from the bone marrow of the donor allows infusion of more CD34+ cells." (PMID 34177941, 2021). "The transplantation of human umbilical cord blood (UCB) CD34+ cells has been successfully used to treat hematological disorders but one major limitation has been the low cell numbers available." (PMID 33298170, 2020). "Human CD34+ HSPCs are a significant tool for gene therapy of some hereditary genetic disorders such as hematological diseases because of their ability to generate a hematopoietic system." (PMID 31186067, 2019). "Lentiviral vector (LVV)-mediated transduction of human CD34+ hematopoietic stem and progenitor cells (HSPCs) holds tremendous promise for the treatment of monogenic hematological diseases." (PMID 30038935, 2018). "The therapeutic effect of circulating CD34+ cells has been demonstrated in hematologic disorders and cardiovascular diseases." (PMID 28666004, 2017).
hematological malignancies (continued). "We thus set out to evaluate the biologic effect of this transgene on human mobilized peripheral blood CD34+ cells, the graft of choice in the setting of gene therapy for genetic hematologic disease." (PMID 26761813, 2016). "More recently, the successful reprogramming of peripheral blood cells such as CD34+ cells, monocytes and T cells allowed the generation of iPS cell lines that model acquired blood disorders." (PMID 24066127, 2013). "This system provides a novel method of generating personalized CD34+ progenitor cells, which can potentially be used for cellular therapy, drug screening, and hematologic disease study." (PMID 22496789, 2012). "Phase I and II clinical trials were conducted in patients with hematologic malignancies and showed that plerixafor plus G-CSF significantly increased the number of circulating CD34+ cells, resulting in increased CD34+ cell yield from apheresis procedures." (PMID 25031928, 2012). "Furthermore, avadomide treatment reduced the number of viable bone marrow CD34+ cells isolated from ZMYM2-FGFR1-positive hematologic malignancy patients." (PMID 35013300, 2022). "Soluble factors released from irradiated human mesenchymal stromal cells (MSC) may induce genetic instability in human CD34+ cells, potentially mediating hematologic disorders." (PMID 35740549, 2022). "In summary, our data suggest that specific components of the secretome from irradiated MSC act as mediators of genetic instability in CD34+ cells, thereby possibly contributing to the pathogenesis of radiation-induced hematologic disorders beyond direct radiation-evoked DNA strand breaks." (PMID 35740549, 2022). "Genetic modification of CD34+ HSPCs offers a cure for monogenic hematological disorders." (PMID 31338385, 2019). "This strategy was initially studied in patients with high risk hematologic malignancies undergoing MSD HCT, utilizing a 2-step selection procedure with a CD34+ selection of stem cells (a minor subset of which expresses CD45RA) followed by depletion of CD45RA+ cells from the CD34− fraction." (PMID 32117310, 2020). "In HIV+ patients with hematological malignancies, gene editing using CRISPR/Cas940 has been used to generate homozygous CCR5-Δ32 deletion in CD34+ cells to introduce HIV resistance." (PMID 31147565, 2019). "For malignant hematological diseases, ≥ 4/6 loci should be matched, with TNC > (2.5–4.0) × 107/kg (recipient weight) and CD34+ cells > (1.2–2.0) × 105/kg (recipient weight)." (PMID 29495966, 2018). "Recently, researchers from the Perugia team have reported outcomes of haploidentical transplantation in 28 patients with hematologic malignancies (AML = 22, ALL = 5, NHL = 1) who received CD34+ selected grafts and Tregs of infusion." (PMID 22046559, 2011). "The discovery of CD34 expression on a diversity of non-hematopoietic precursor cells will help increase the role of CD34+ cells in the therapy of pathologies beyond blood disorders." (PMID 37241170, 2023). "The results provide a framework for the preclinical evaluation of prime editing in CD34+ HSPCs for the correction of hematological disorders not just limited to SCD." (PMID 36605051, 2022). "CD34+ cell count/kg bw in the graft has been shown to be predictive for survival in different haematological diseases following PB-HSCT (CD34+ > 4.5 × 106/kg bw only 18 CML patients) and BM-HSCT (CD34+ > 3 × 106/kg bw; 55 patients with CML, of which 11 accelerated phase and 2 in BC)." (PMID 34331022, 2021). "Generation of DC from CD34+ hematopoietic stem and progenitor cells (HSPCs) may provide potential in patients undergoing allogeneic HSPC transplantations for hematologic malignancies." (PMID 29867960, 2018). "Previous hematologic diseases, hemoglobin, platelet count, and expression of CD34 at diagnosis had no impact on OS in these elderly AML patients." (PMID 27472687, 2016).
hematological malignancies (continued). "Importantly, of the vesicle populations studied, the CD34+/CD71low cluster showed statistically significant differences between DBA patients and healthy controls or patients with other haematological diseases." (PMID 26394034, 2015). "Therefore, other haematological disorders should be ruled out when the number of circulating CD34-positive cells increases." (PMID 41540281, 2026). "The results showed thatthe level of mLOY in both CD34+ and CD3+ cells were agedependentin men without hematological diseases, and inthe case of CD34+ cells, it was significantly higher in MDSpatients compared to elderly control men without hematologicalpathologies." (PMID 37808213, 2023). "Specific factors released from irradiated human mesenchymal stromal cells (MSC) may induce genetic instability in non-irradiated human CD34+ cells potentially mediating hematologic disorders." (PMID 35740549, 2022). "It has been reported that HSC and HPC numbers in UCB were adequate for the treatment of hematopoietic diseases in children and not adults as it is been estimated that for successful engraftment at least 2.5 × 106 CD34+ cells per kilogram of patient body weight is required." (PMID 33298170, 2020). "CD34+ UCB cells have been successfully cultured and expanded in pre-clinical studies and in clinical studies in adult hematological malignancies, but there are no clinical trials testing the use of an expanded CD34+ product in neonates." (PMID 35259278, 2022). "For nonmalignant hematological disease patients, ≥ 5/6 loci should be matched, with TNC > 3.5 × 10^7/kg (recipient weight) and CD34 + cells > (1.7 × 10^5/kg (recipient weight)." (PMID 34526099, 2021). "For non-malignant hematological diseases, ≥ 5/6 loci should be matched, with TNC > 3.5 × 107/kg (recipient weight), and CD34+ cells > (1.7 × 105/kg (recipient weight)." (PMID 29495966, 2018).
cardiovascular disease (38 papers, 2009 to 2025). "Circulating CD34-positive cell counts were reported to be inversely associated with cardiovascular disease-related mortality, while height loss was reported to be positively associated with cardiovascular disease." (PMID 41391851, 2025). "We previously evaluated the association of CD34+ cells with cardiovascular disease (CVD) events over 23 months, but long-term CVD outcomes in relation to levels of CD34+ cells in patients on maintenance hemodialysis are unclear." (PMID 31584974, 2019). "Recent studies have revealed an inverse association between height and cardiovascular disease and that endothelial progenitor cells (CD34-positive cells) contribute to vascular maintenance, which is associated with cardiovascular disease." (PMID 30695751, 2019). "CD34+ endothelial Progenitor Cells (EPCs) are responsible for endothelial repair and neo-angiogenesis and can be used as a cardiovascular disease risk biomarker." (PMID 29724198, 2018). "A previous study also reported that myocardial necrosis with simultaneous elevation of VEGF and SDF-1α caused significant CD34-positive cell elevation in patients with cardiovascular disease." (PMID 27374094, 2016). "However, an inverse association between circulating CD34-positive cell count and cardiovascular disease has been reported." (PMID 36528703, 2022). "Therefore, the present results showing a significant inverse association between circulating CD34-positive cell count and height loss can help clarify the potential mechanism for the association between height loss and cardiovascular disease." (PMID 35504933, 2022). "Therefore, circulating CD34-positive cell count could be inversely associated with cardiovascular disease because it reflects active maintenance of the microcirculation." (PMID 36528703, 2022). "Participants with low levels of circulating CD34-positive cells might have a higher risk of cardiovascular disease than those with high levels of circulating CD34-positive cells because low levels of CD34-positive cells indicate a deficiency in endothelial repair." (PMID 35159980, 2022). "In the recent years, trials have been made to explore the potential of CD34+ cell therapy for the treatment of different cardiovascular diseases." (PMID 38424230, 2024). "Older adults exhibit a reduced number and function of CD34 + circulating progenitor cells (CPC), a known risk factor for cardiovascular disease." (PMID 36786845, 2023). "Previous studies confirmed the role of bone marrow-originated Cd34-derived myeloid cells in cardiovascular diseases, which is a distinct developmental origin from their tissue-resident mesenchymal cells and EC counterparts." (PMID 37147443, 2023). "Not only are circulation CD34+ cells recognized as endothelial progenitors, effective in treatment of cardiovascular diseases, but local CD34+ cells are also believed to be crucial for angiogenesis." (PMID 36358355, 2022). "Particularly, CD45+CD34+MPCs population have shown their role as useful biomarkers of cardiovascular diseases." (PMID 31069956, 2019). "CD34+KDR+ CACs are markers of vascular injury although the mechanisms for their increases or decreases in the circulation of patients with cardiovascular diseases are unclear." (PMID 28278173, 2017). "In patients with cardiovascular disease, numbers of circulating CD34+KDR+ EPC are inversely related to vascular damage." (PMID 23936333, 2013). "Importantly, it is noted that an increased number of circulating CD34+CD133+ EPCs is associated with better outcomes of physical function and cardiovascular diseases." (PMID 38854406, 2024). "Additionally, there have been numerous clinical reports on the use of CD34+ cell therapy for treating cardiovascular diseases." (PMID 39388398, 2024). "CD34 is one of the endothelial progenitor cell markers, and CD34+ cells have been used in cell therapy for regenerating endothelial cells and promoting angiogenesis in cardiovascular diseases." (PMID 36672176, 2023).
cardiovascular disease (continued). "Since the isolation of CD34+ “putative EPCs” from peripheral blood mononuclear cells, many clinical studies reported that CD34+ cell therapy could treat cardiovascular diseases." (PMID 37147443, 2023). "However, the predictability of the circulating CD34-positive cell number for the occurrence of cardiovascular events has yet to be reported in other cardiovascular diseases." (PMID 31360266, 2019). "Recently, Hammadah measured CD34+ cells in CHD patients and found that their low levels in circulation independently predict adverse cardiovascular disease outcomes." (PMID 30737465, 2019). "However, the available clinical studies with respect to administration of circulating progenitor cells in cardiovascular diseases are mainly about CD34+ cells; only a few studies suggest the role of CD34+/CD133+ cells in cardiovascular diseases." (PMID 25984328, 2013). "We determined that in human subjects without known cardiovascular disease that the quantity of CD34+ HSPCs in the bloodstream positively corresponds with plasma LDL concentration." (PMID 23991206, 2013). "We performed a blinded, randomized observational study in human subjects with no history of cardiovascular disease events to determine the relationship between serum lipid levels and the circulating CD34+ HSPCs." (PMID 23991206, 2013). "In this study, we identified that hypoxia upregulates BNIP3 gene expression in young, but not aged, CD34+ EPCs, indicating a potential role of BNIP3 in aging-related cardiovascular diseases." (PMID 29708992, 2018). "Verification of the migration assay in BM cells from subjects without a cardiovascular disease background confirms the depletion of CD3+ lymphocytes and CD34+ and CD133+ PCs along with enrichment of CD14++CD16−, CD14++CD16+ and CD14+CD16++ monocytes in the SDF-1-attracted fraction." (PMID 25889213, 2015).
adenocarcinoma (11 papers, 2002 to 2025). A common cancer characterized by the presence of malignant glandular cells. "Our analysis revealed an association for CD34+ CAFs with G1/2 tumors and adenocarcinoma histology." (PMID 31760702, 2020). "The adventitia participates in artery remodeling and the role of the adventitial CD34+SCs/TCs in the arterial intimal thickening in adenocarcinomas of colon also requires further study." (PMID 33072740, 2020). "Infiltrative adenocarcinomas of the colon showed a desmoplastic reaction in the submucosa and serosa, in which numerous elongated stromal cells around the neoplastic glands presented αSMA expression (myofibroblastic phenotype) and were negative for anti-CD34." (PMID 33072740, 2020). "Immunohistochemically, adenocarcinoma expresses epithelial markers such as CK and EMA, but negative for CD31, CD34 and especially CAMTA1 and TFE3." (PMID 40040722, 2025). "When performing the same analyses on the synchronous adenocarcinomas, all cases proved to be negative for CD117 and CD34." (PMID 33335133, 2020). "All adenocarcinomas were negative for CD117 and CD34, whereas positive DOG1 immunostaining was detected in four cases." (PMID 33335133, 2020).
benign tumor (9 papers, 1998 to 2025). "RAH is a rare benign tumor, and the positive staining of markers, including ERG, FLI-1, CD31 and CD34, can contribute to its differential diagnosis." (PMID 40416971, 2025). "Reduced factor VIII-related antigen compared with CD31 and CD34 immunostaining was observed in both borderline and malignant mucinous and serous tumours (P < 0.02) but not in benign tumours (P > 0.05)." (PMID 9649134, 1998). "However, compared with the model group, the expressions of CD34 and α-SMA were markedly elevated in the HXWTF and isosorbide mononitrate treatment groups, suggesting that HXWTF promotes vessels generation in ischemic heart." (PMID 31938036, 2020).